KRAS (KRas proto-oncogene, GTPase)
Diseases named in the same sentence as KRAS in open-access papers (continued):
Sharing a sentence is not in itself a finding about the gene and the disease.
cancer (continued). "The PentaPanel platform assesses single nucleotide polymorphisms in 56 hotspots of the 5 most clinically relevant cancer genes, KRAS, NRAS, BRAF, EGFR and PIK3CA for a total of 221 detectable mutations." (PMID 26435479, 2015). "Only those IQcs with high G4 ΔTm values (2d and 3e) showed 5–10 fold superior activity against KRAS-dependent cancer cell lines than against cell lines expressing wt KRAS (MCF7 and lung fibroblasts)." (PMID 25853628, 2015). "The targeted sequencing of other cancer-related genes, including KRAS, BRAF, CDKN1A, KIT (abstract only), JAK2, FOXL2, IDH1, AKT1 and EZH2 did not reveal any pathogenic mutations." (PMID 26415226, 2015). "Moreover, cancer cells with different KRAS mutations may have different metabolic profiles." (PMID 25514600, 2015). "We established a non-cancer colon NCM460 cell model to study, in the same genetic background, the effect of overexpressing three of the most common mutant KRAS alleles that occur in CRCs: KRASG13D, KRASG12D and KRASG12V." (PMID 26418750, 2015). "Treatment of KRAS mutant tumors still largely relies on conventional chemotherapy, which commonly results in poor response rate and development of drug resistance in cancer patients." (PMID 25946136, 2015). "Companion diagnostics for hotspot mutations of EGFR, KRAS, BRAF, and ALK, which are clinically associated with specific targeted cancer therapies, are currently available for LUADs." (PMID 26084335, 2015). "NSC-743380 is highly active (median growth inhibitory concentration [IC50] between 10 nM and 1 M) in vitro in 30 of 102 cancer cell lines tested, including many KRAS mutant cancer cells." (PMID 25514600, 2015). "In particular, several miRNAs that suppress cancer growth in a healthy cell are found at lower levels in mutant KRAS cells." (PMID 26132860, 2015). "While mutations in KRAS, BRAF, PIK3CA, and EGFR were found in cancer types expected, there were also several instances of actionable mutations identified in diseases for which these mutations have not been well characterized." (PMID 26015395, 2015). "In human cell lines derived from pancreatic and other cancers, dependence on KRAS signaling correlates with expression of specific gene signatures, including genes whose activity is required to sustain RAS activity and malignancy." (PMID 26151762, 2015). "In this study, we report that human oncogenic KRAS driven by the zebrafish krt5 or gfap promoter induces malignant tumors of the nervous system." (PMID 25644510, 2015). "In summary, we uncovered the impact of the RAL signal transduction on genetic program and growth control in KRAS- and BRAF-mutated colorectal cells and demonstrated prognostic potential of the pathway-responsive gene signature in cancer patients." (PMID 26033452, 2015). "BPTES pre-treatment sensitized a variety of NQO1-expressing KRAS mutant cancer cell lines to ß-lap, including lung, triple-negative breast, and additional PDA cell lines." (PMID 26462257, 2015). "Our analysis reveals that oncogenic KRAS dependency can be relinquished in KRAS-initiated tumors, and that some cancer cells can shuttle between the KRAS-dependent (drug-sensitive) and independent (drug-tolerant) states." (PMID 26158412, 2015). "In fact, the presence of constitutively active KRAS sensitizes cancer cells to MEK and BCL-XL or RAF inhibition, TRAIL, 5-FU and oxaliplatin." (PMID 26028667, 2015). "More recently, new guidelines for the use of cetuximab and panitumumab treatment in CRC patients supported the analysis of the mutational status of both KRAS and NRAS genes and BRAF in wild-type RAS cancers." (PMID 26508446, 2015).
cancer (continued). "To transpose our findings to more clinically relevant cancer models, we used the reverse approach by silencing KRAS in two CRC-derived cell lines harboring different KRAS activating mutations." (PMID 26418750, 2015). "The mutated KRAS oncogene is found in approximately 90% of cases of PDAC, and generally in about 30% of human cancers." (PMID 26158412, 2015). "Semi-quantitative assessment of the contribution of each isoform to total Ras protein abundance indicated that KRAS was frequently the most abundant isoform across a panel of cancer cell lines." (PMID 26560143, 2015). "A possible explanation is that KRAS mutant cancer cells can be categorized as KRAS-dependent and KRAS-independent, and that RAS activation signatures are observed in substantial numbers of RAS wilt-type tumors." (PMID 25514600, 2015). "miR-4689 expression was significantly down-regulated in cancer tissues compared to normal mucosa, and it was particularly decreased in mutant KRAS CRC tissues." (PMID 25756961, 2015). "Overall, these data indicate that the epigenetic changes established in KRAS mutant cancers makes them insensitive to killing by RAS pathway inhibitors, while disrupting the balance between acetylation and deacetylation sensitizes them to the treatment." (PMID 26158412, 2015). "In cases with wild-type KRAS, BRAF and PIK3CA a number of cancer-associated genes representing potential drivers were identified (for example, STK11, GNAS, CHEK2 and RB1)." (PMID 25855536, 2015). "A recent synthetic lethality screen of MEK inhibitor (AZD6244) in KRAS mutant cancer identifies the anti-apoptotic gene BCL-XL as the top hit." (PMID 26439693, 2015). "Particularly, there were 88 DEGs (hypergeometric P = 0.0019) that overlap with the known cancer genes, including PDAC related genes such as MYC, BRCA1, and KRAS, which indicates that the DEGs of this study have close bond with the cancer progression indeed." (PMID 26425543, 2015). "For cancers with KRAS mutations, much research has been focused on KRAS4B, since KRAS4B transcript was shown to be more abundant." (PMID 26715448, 2015). "Eighteen (6.3%) cancers were found to harbor RAS missense mutations, including 15(5.3%) in KRAS, 2(0.70%) in NRAS and 1(0.4%) in HRAS." (PMID 25669975, 2015). "Accordingly, Noxa levels are unaffected by oncogenic KRAS expression and other pathways, such as the ones controlled by PI3K/AKT, protect cancer cells from the potentially pro-apoptotic stimulus of mutated KRAS." (PMID 26028667, 2015). "This strategy allowed us to exclude numerous potential background disorders of miRNAs, caused by various genetic and epigenetic alterations observed in cancer, which facilitated the identification of miRNAs induced solely by KRAS gene alterations." (PMID 25756961, 2015). "Because many ongoing trials have adopted co-targeting the KRAS-mediated MAPK and PI3K signaling as the prevalent therapeutic approach, we have explored cancer-specific vulnerabilities associated with epigenetic deregulation." (PMID 26158412, 2015). "Wnt/β-catenin signaling has been identified as a potential mediator of resistance to MEK inhibition and strong synergy has been observed for the combination of MEK and tankyrase inhibition in KRAS-mutant cancer cells." (PMID 26513298, 2015). "Our previous studies revealed that NSC743380 is highly active in a number of KRAS mutant cancer cell lines." (PMID 25514600, 2015). "We also confirmed the same point mutations in KRAS and PBRM1 in the DNA of the primary carcinoma by Sanger sequencing." (PMID 26669280, 2015). "Both KRAS- and BRAF- mutated tumors were more likely to be located at proximal colon than wild-type (WT) carcinomas." (PMID 25929517, 2015).
cancer (continued). "The present study is a de novo KRAS pathway analysis of carcinoma cells within their native tissue microenvironment." (PMID 26468985, 2015). "KRAS copy number was also positively correlated to KRAS protein levels in a panel of cancer cell lines." (PMID 24874471, 2014). "KRAS is upregulated in different cancer types, and post-transcriptional regulation of KRAS via interaction with miR-216a/217 was reported in vitro." (PMID 25052703, 2014). "This query returns the average methylation results for the KRAS gene of all patients in a particular cancer histology." (PMID 25937882, 2014). "This suggests a model where the KRAS coupling to specific cancers is due to its role in expanding cancer progenitor cells in these tissues." (PMID 25109951, 2014). "Here, we report that KRAS is targeted by miR-200c, which results in a slower proliferation and in an altered cell cycle of cancer cells." (PMID 24368337, 2014). "Further work will be necessary to define the role of KRAS amplification in cancer metastases and in drug resistant tumors, especially in tumors that have acquired resistance to receptor tyrosine kinase inhibitors." (PMID 24874471, 2014). "REOLYSIN is a proprietary formulation of human reovirus, a naturally occurring oncolytic virus that preferentially replicates in cancer cells with activated KRAS." (PMID 24722523, 2014). "Another interesting result obtained in our study was the increased expression of DNMT1, the enzyme that methylates promoters of tumor suppressor genes in cancer cells, in NSCLC with KRAS mutations." (PMID 25222473, 2014). "Despite the overwhelming evidence suggesting importance of both NQO1 and KRAS in the pathogenesis of cancers, we are aware of only a single study investigating possible associations between them." (PMID 25222473, 2014). "Correspondingly, it has been shown that the over-expression of p16ink4a is dominant to the effects of KRAS in cell culture models and is capable of re-establishing a senescence-like arrest in established cancer models." (PMID 25156567, 2014). "A recent study identified the basis of different activity of MEK inhibitors in BRAF versus KRAS mutant cancers." (PMID 24722523, 2014). "The preferential oncolysis of KRAS mutant cancer cells by reovirus prompted us to investigate this as a potential therapeutic option for these patients." (PMID 24798549, 2014). "We found recurrent mutations in 4 cancer genes and delineated that NRAS, KRAS and ATM mutations are distributed in a mutually exclusive fashion." (PMID 25115387, 2014). "In KRAS-transformed cells, the oncoprotein results in changes in cell adhesion and migration properties, and, thus, the metastatic potential of the cancer cells." (PMID 25287248, 2014). "While microRNAs (miRNAs) and the KRAS oncogene are known to be dysregulated in various cancers, little is known about the role of miRNAs in the regulation of KRAS in cancer." (PMID 25433809, 2014). "We have previously conducted several studies on the role of MSI, methylation of cancer related genes and mutations of known genes such as BRAF and KRAS, as well as microarray based studies of CRC tumors from different patients' populations." (PMID 24475022, 2014). "Changes in the normal ratio of transitions to transversions in KRAS have been reported in several cancers including subtypes of chronic lymphocytic leukemia and esophageal cancer." (PMID 25158139, 2014). "The let-7 miRNA family, which was the first reported group of TSmiRNAs in cancer, represses a number of oncogenic proteins such as KRAS, high mobility group AT-hook 2 (HMGA2), and v-myc myelocytomatosis viral oncogene homolog (MYC)." (PMID 24551595, 2014).
cancer (continued). "Despite this, KRAS is the most frequently mutated isoform and mutation of each RAS protein exhibits coupling with a specific subset of cancers." (PMID 25109951, 2014). "Instead, we here propose that an alternative approach is to eliminate KRAS protein from the cancer cell." (PMID 25093678, 2014). "The sensitivity of the assay was determined after isolation of KRAS mutant cancer cells spiked into healthy donors' blood, using the CellSearch Epithelial Cell kit." (PMID 25137394, 2014). "The results demonstrated that the WEnCA technique is a sensitive and convenient technique that produces easy-to-interpret results for detecting activated KRAS from the peripheral blood of cancer patients." (PMID 24884535, 2014). "Here we review the studies published in 2014 that explored miRNA-mediated regulation of KRAS in different cancers." (PMID 25433809, 2014). "SSAs and MSI cancers were reported to exhibit similar features including predominant location in the proximal colon, high BRAF and low KRAS mutation and enhanced DNA hypermethylation." (PMID 24964857, 2014). "Associations of KRAS mutational status with progression, treatment outcome, and response to EGFR-based treatment have been reported in both of these cancers." (PMID 25158139, 2014). "Absolute quantification of RAS isoform protein abundance in normal tissues has not been performed to date; however, comparative analysis of RAS isoform protein levels in a panel of cancer cell lines revealed that KRAS is typically the most abundant isoform." (PMID 25109951, 2014). "KRAS-induced cancers are very common, yet despite intense efforts, effective therapies for these malignancies are sofar unavailable." (PMID 24955217, 2014). "It has been reported that BT474 and MDA-MB-361 are Her2 high-expressing, and BT20 and MDA-MB-231 are Her2 low-expressing cancer cells, and that BT20, MDA-MB-361, and BT474 have mutations in PIK3CA, and only MDA-MB-231 has KRAS mutation among these cell lines." (PMID 25159299, 2014). "Both KRAS and BRAF mutations fall into the “driver mutation” classification, since it appears to be one of the first events in the malignant transformation to cancer." (PMID 25361007, 2014). "In animal experiments, oncogenic KRAS and activated BRAF mutations cooperate to accelerate the rapid onset of cancer." (PMID 25013473, 2014). "The concomitant occurrence of PIK3CA and KRAS mutations was reported previously in CRC and other human cancer types." (PMID 25367198, 2014). "KRAS copy number was negatively correlated with shRNA score, suggesting that cancer cell lines with KRAS amplification are most sensitive to Kras shRNA-mediated cell death." (PMID 24874471, 2014). "The sensitivity of our experimental approach to determine accurately the KRAS mutation status in a limited number of CTCs present among normal blood cells in circulating blood was validated by spiking KRAS mutant cancer cells into the blood of healthy donors." (PMID 25137394, 2014). "Another shRNA screening study identified target genes that effectively cooperated with MEK inhibitors in KRAS-mutant cancers, suggesting a therapeutic potential for a combination of MEK and BCL-XL inhibitors." (PMID 24297677, 2014). "KRAS-mutant cancer is unresponsive to EGFR inhibitors because oncogenic KRAS is not dependent on upstream activation by EGFR." (PMID 25004126, 2014). "On the other hand, the KRAS protein was significantly up-regulated in cancer cells by up to 3.57-fold despite down-regulated mRNA levels." (PMID 25287248, 2014).
cancer (continued). "BRAF and KRAS are upstream activators of the mitogen-activated protein kinase (MAPK) cascade which is commonly hyper-activated in different types of human cancer." (PMID 24139521, 2013). "Although STK33 has not been directly associated with body mass regulation previously, it is of particular interest because of its potential involvement in GTPase KRas (KRAS) driven cancers and the fact that STK33 has also been targeted pharmacologically." (PMID 23967198, 2013). "Rs4929949 is located within intron 1 of the gene encoding STK33, a pharmacologically targeted serine/threonine kinase reported to be involved in KRAS-mediated cancers." (PMID 23967198, 2013). "Mutational analysis for KRAS and BRAF discloses some possible interactions between different tumorigenic pathways of low- and high-grade carcinomas." (PMID 23388101, 2013). "The effects of combining GDC-0973 and the PI3K inhibitor GDC-0941 on the proliferation of BRAF and KRAS mutant cancer cells indicated combination efficacy both in vitro and in vivo." (PMID 23085539, 2012). "These important results were obtained by performing washout studies in vitro and alternate dosing schedules in mice with MEK and PI3K inhibitors with BRAF and KRAS mutant cancer cells." (PMID 23085539, 2012). "Survivin is a transcriptional target of both Wnt and KRAS pathways and has a crucial role in the survival of KRAS-driven cancer." (PMID 23227266, 2012). "Attempts have been made at targeting KRAS for cancer treatment including inhibition of protein expression through antisense oligonucleotides and with blockage of posttranslational modifications to inhibit downstream effectors." (PMID 22997602, 2012). "Considering the compensatory relationship between RAS/RAF/ERK and PI3K/AKT/mTOR pathways, KRAS mutant cancer cell lines have shown a synergistic effect of PI3K and MEK inhibitors." (PMID 22159814, 2012). "Despite this, in our opinion, the in vitro results presented here represent a convincing proof-of-principle for double pharmacologic targeting and encourage the development of clinical β-catenin and KRAS inhibitors for targeted cancer therapy." (PMID 23227266, 2012). "The study will include patients with metastatic CRC who have received previous therapy for their disease and whose cancers have a mutant KRAS gene." (PMID 23085539, 2012). "The reduced expression of let-7 in cancer tissues corresponds to significantly higher levels of KRAS mRNA." (PMID 23202889, 2012). "The findings of AKT dephosphorylation by PDE4 inhibitor, rolipram or PDE4B2-shRNAs in HCT116 cells in 3 DC, but not in HCT116 cells in 2 DC, suggesting the 3-D specific action of PDE4B2 for cancer cells with oncogenic KRAS." (PMID 22830422, 2012). "The overall mutation frequency of KRAS, BRAF and PIK3CA in our HNSCC samples was lower than reported for other cancers." (PMID 22994622, 2012). "Further research is required to determine more precisely how let-7 is regulated and if its expression or the expression of its repressor(s) can be used to target KRAS-driven cancers." (PMID 23202889, 2012).